MIR7159 (microRNA 7159)
Synonyms: hsa-mir-7159
Gene: MicroRNA gene on chromosome 6 (33,899,135 to 33,899,200, forward strand). Ensembl gene ENSG00000276824.
Homologues: Orthologues: chimpanzee MIR7159 (100% identical).